SIRT1 (sirtuin 1)
Diseases named in the same sentence as SIRT1 in open-access papers (continued):
Sharing a sentence is not in itself a finding about the gene and the disease.
acute kidney injury (continued). "In fact, Sirt1 expression appears to protect against ischemia/reperfusion-induced acute kidney injury and unilateral ureteral obstruction induced renal injury in mouse models." (PMID 25653823, 2015). "In the present study, we investigated the role of Sirt1 in LPS-induced acute kidney injury by inducible deletion of Sirt1 in mice." (PMID 24896770, 2014). "The results indicate that Sirt1 is protective against LPS-induced acute kidney injury by suppressing kidney inflammation and down-regulating inflammatory signaling." (PMID 24896770, 2014). "In a mouse model of sepsis-induced acute kidney injury, tetrahydrocurcumin elevated survival rates, improved kidney function, reduced inflammatory response and oxidative stress, and prevented cell apoptosis through increased SIRT1 expression." (PMID 37630770, 2023). "Studies have suggested Evs may ameliorate acute kidney injury (AKI) induced by CLP via the sirtuin-1 (SIRT1) signal pathway." (PMID 38343439, 2023). "Moreover, curcumin exerted protective kidney effects in a rat model of gentamicin-induced acute kidney injury, reduced the apoptosis of tubular cells, reduced oxidative stress and induced SIRT1 and Nrf2/HO-1 expression." (PMID 35807694, 2022). "Furthermore, in a mouse model of acute kidney injury exosomes derived from adipose tissue mesenchymal stem cells were found to mediate a renal protective effect by the activation of the SIRT1 pathway." (PMID 36170022, 2022). "In addition, SIRT-1 is also involved in the pathogenesis of diseases such as acute kidney injury, craniocerebral trauma, and aortic sclerosis." (PMID 34315467, 2021). "Moreover, a recent report showed that Sirt1 retards calcification of vascular smooth muscle cells in a rat model of renal failure." (PMID 22493735, 2012). "EETs derived from CYP2J2 overexpression protected I/R-induced rat acute kidney injury (AKI) through activation of autophagy by upregulating the Sirt1/FOXO3a signaling pathway." (PMID 35744996, 2022). "Recently, hypoxia-inducible factor (HIF)-2α and Beclin1 were added to the list of SIRT1-target proteins with implications in acute kidney injury (AKI); these are described in later sections of this review." (PMID 35277012, 2022). "SIRT1, an NAD+-dependent deacetylase, exhibits decreased expression and activity during inflammation and in acute kidney injury induced by various agents." (PMID 40006061, 2025). "Resveratrol, as an SIRT1 activator, alleviates acute kidney injury in cecal ligation and puncture (CLP) septic mice by activating SIRT1 to promote deacetyl-mediated autophagy." (PMID 37628912, 2023). "In addition, specific overexpression of Sirt1 in the kidney in AKI induced by the chemotherapeutic drug cisplatin preserved peroxisome function to prevent acute kidney injury." (PMID 35126819, 2022). "Despite these limitations, the identification of a temporal decline in SIRT1 levels among CI-AKI patients provides a valuable signal and supports the need for further research evaluating SIRT1 as a component of dynamic biomarker panels for acute kidney injury." (PMID 40507714, 2025). "With the increase of age, the levels of SIRT1 and NAD+ in organisms will gradually decrease; significantly, the decrease of SIRT1 and NAD+ in the kidneys of elderly organisms will lead to an increase in the incidence of acute kidney injury." (PMID 39411062, 2024). "Studies indicate that BAM15 may activate AMPK in the early stages of septic acute kidney injury (AKI) and silent information regulator sirtuin 1 (SIRT1) in the later stages, thereby increasing NAD+ levels and promoting PGC-1α production." (PMID 37900126, 2023).
acute kidney injury (continued). "Previous research showed that this metabolite ameliorated the inflammatory response by decreasing the expression of the cytokines TNF-α and IL-6 in a mouse model of sepsis-induced acute kidney injury (AKI), and this effect was dependent on silent information regulator sirtuin 1 (SIRT1) signaling." (PMID 38067518, 2023). "After ICH, although total SIRT1 expression increased, mitochondrial proteins, such as ATPβ, NDUFB8, and COX I, were reduced in the ICH group compared with shams, and this was also reported in acute kidney injury." (PMID 29375306, 2017). "As aged kidneys have decayed NAD+ metabolism and reduced levels of SIRT1, supplementation with NMN can efficiently restore NAD+ levels and protect aged mice against cisplatin-induced acute kidney injury (AKI)." (PMID 33609766, 2021). "Similarly, studies have also shown that quercetin can activate SIRT1, enhance the Nrf 2/HO-1/SOD1 signaling pathway, inhibit apoptosis and M1 macrophage polarization, and exert anti-inflammatory and antioxidant effects, thereby reducing contrast-induced acute kidney injury in type 1 diabetic mice." (PMID 39655278, 2024). "Similarly, it isconceivable that other pathologies not studied in our work, such ascardiovascular or renal failure, could be insensitive to Sirt1 or may requirehigher levels of Sirt1 to be ameliorated." (PMID 20562473, 2010).
liver cancer (73 papers, 2010 to 2025). An epithelial or non-epithelial malignant neoplasm that arises from the liver. "To further confirm that KLF14 inhibits the growth of liver cancer cells through interacting with SIRT1, we performed mutated KLF14 (KLF14-M4) stably overexpressed HCC cells." (PMID 36600258, 2023). "Despite the prevalence of HCC and its association with c-Myc and SIRT1, there have been few reports describing the biologic role of SIRT1 in liver cancer." (PMID 23024800, 2012). "Clinically, SIRT1 overexpression is associated with vascular invasion, metastasis, and sorafenib resistance, highlighting its potential as a prognostic biomarker and therapeutic target for aggressive liver cancers." (PMID 41008982, 2025). "Moreover, SNHG7 has been demonstrated to inhibit NLRP3-associated pyroptosis through regulating miR-34a/SIRT1 axis in liver cancer." (PMID 37441551, 2023). "SIRT1 transgenic mice exhibit reduced susceptibility to carcinogen-induced liver cancer." (PMID 26318035, 2015). "Interestingly, in a mouse model of metabolic syndrome-associated liver cancer, overexpression of SIRT1 reduced the susceptibility to liver cancer and improved hepatic protection from both DNA damage and metabolic damage." (PMID 22745910, 2012). "In contrast to activators, SIRT1 inhibitors have shown therapeutic promise in certain contexts, particularly in treating liver cancers such as HCC." (PMID 40052151, 2025). "PARP inhibition increases NAD+ levels, enhances SIRT1 activity, boosts mitochondrial function, and modulates liver cancer." (PMID 40427612, 2025). "For instance, low expression of miR-425 can elevate SIRT1 levels, thereby stimulating pro-survival lipophagy and enhancing resistance to sorafenib in liver cancer." (PMID 39403142, 2024). "Overall, these findings support the novel evidence that the pivotal role of c-Myc and SIRT1 is critically involved in Isoimperatorin-induced apoptosis in HCCs as potent molecular targets in liver cancer therapy." (PMID 38673833, 2024). "Herein, in line with the function of SIRT1 in the senescence of liver cancer cells reported by Wang, the anti-tumor and senescence-facilitating function of Neratinib in AU565 cells were accompanied by sharply downregulated SIRT1." (PMID 38829772, 2024). "Taken together, it can be concluded that Isoimperatorin induced apoptosis via the pivotal role of c-Myc and SIRT1 in HCCs as a potent candidate for liver cancer therapy." (PMID 38673833, 2024). "Sirtuin 1 (SIRT1) is overexpressed in liver cancer and acts as a tumor promoter through deacetylation by sex-determining region Y-box 2 (SOX2)." (PMID 39281271, 2024).
liver cancer (continued). "miR-124-3p modulates sirtuin 1 expression in liver cancer, thereby attenuating the growth of liver cancer cells." (PMID 37697333, 2023). "The SNHG7/miR-34a/SIRT1 axis played an important role in liver cancer progression via modulation of NLRP3-dependent pyroptosis." (PMID 36387211, 2022). "It decreased the levels of liver dysfunction biomarkers (SGPT and SGOT), lipid peroxidation (LPO), and stimulated SIRT1 to inhibit NF-κB, thereby increasing the sensitivity of liver cancer cells to TNF-α-induced apoptosis." (PMID 36278230, 2022). "Previous studies demonstrated that SIRT1 functions as a promotor of liver cancer and its level is significantly decreased by capsaicin in bladder cancer cells." (PMID 35674129, 2022). "Our results pointing to a proinflammatory role of SIRT1 overexpression are in agreement with previous work in liver cancer in which SIRT1 promoted proinflammatory cytokine expression in macrophages." (PMID 34952202, 2022). "For instance, miR‐486 suppresses the expression of OCT4 and reduces cancer stemness through targeting Sirt1 in liver cancer." (PMID 35253323, 2022). "Studies have found that capsaicin can inhibit the occurrence of liver cancer through the SIRT1/SOX2 signaling pathway." (PMID 36278230, 2022). "SIRT1 levels in normal liver tissue are very low, but overexpression in liver cancer tissues and cell lines shows that SIRT1 has a key role in liver cancer." (PMID 36081910, 2022). "In breast, lung, and liver cancers, Sirt1 functions as an oncogene to promote cancer cell proliferation." (PMID 33854041, 2021). "Liu reported that Sirt1 is highly expressed in liver cancer stem cells and decreases during differentiation, and that high levels of Sirt1 predict a decreased probability of survival of patients with HCC." (PMID 32570218, 2020). "It has been reported that human ribosomal protein S3 (RPS3) regulates the expression of silent information regulator 1 (SIRT1) after transcription to promote liver cancer." (PMID 33228611, 2020). "SOX2 is a main downstream regulator of SIRT1‐mediated self‐renewal and tumorigenic potential of liver cancer stem cells, and SOX2 is amplified and drives proliferation in small-cell lung cancer." (PMID 32055024, 2020). "Long noncoding RNA HULC accelerates growth of liver cancer stem cells by enhancing the expression of Sirt1 dependent on miR675 and then inducing the cellular autophagy to increase CyclinD1 and pRB in human liver cancer stem cells." (PMID 31900225, 2020). "Here, we present the interaction between SIRT1, miRNAs, and liver cancer stem cells and discuss the consequences of their interplay for the development and treatment of HCC." (PMID 31608282, 2019). "Collectively, data from the present and previous studies support a pro-tumorigenic role for SIRT1 in liver cancer." (PMID 26824501, 2016). "Our findings are in agreement with previous studies demonstrating that SIRT1 downregulation inhibits proliferation of lung, colorectal, thyroid, breast, prostate and liver cancer cell lines." (PMID 25915617, 2015). "Based on our in vitro experiments, the effect of SIRT1 in an ectopic model of liver cancer metastasis was subsequently tested." (PMID 25522783, 2014). "A positive correlation of SIRT1 expression and Ki67 index has also been reported in liver cancer and the expression level of SIRT1 was directly correlated with the proliferative potential of tumor cells." (PMID 24019980, 2013).
liver cancer (continued). "In line with the positive correlation between c-Myc and SIRT1 expression in Tet-O-MYC liver cancer cells, we detected a significant immunohistochemical relationship between SIRT1 and c-Myc in human HCCs." (PMID 23024800, 2012). "The effect of either over-expression or knock down of SIRT1 on cell proliferation and survival was evaluated in both mouse and human liver cancer cells." (PMID 23024800, 2012). "Another aspect of novelty in our work is theemployment of a new model of diet-promoted liver cancer and the demonstrationthat Sirt1 is a potent protector of this type of liver carcinogenesis." (PMID 20562473, 2010). "Inhibits NLRP3-dependent pyroptosis via miR-34a/SIRT1 axis in liver cancer." (PMID 39267831, 2024). "We further investigated whether doxorubicin induces SIRT1 ISGylation in cell lines derived from lung, cervical, breast or liver cancer." (PMID 38443596, 2024). "Additionally, in a rat primary liver cancer model, MSCs with high expression of SIRT1 (Ad-Sirt1-MSCs) promoted macrophage recruitment and synergistically facilitated liver cancer occurrence by secreting C–C chemokine ligand 5 (CCL5)." (PMID 37670393, 2023). "Importantly, SIRT1 suppressed the expression of IRP2 in liver cancer cells at mRNA and protein levels." (PMID 36600258, 2023). "SIRT1 is overexpressed in liver cancer and acts as a tumor promoter via SOX2 deacetylation." (PMID 35674129, 2022). "Interference with SNHG7 down-regulated the expression of SIRT1, but up-regulated the levels of NLRP3, caspase-1, and interleukin-1beta, which induced pyroptosis, suggesting NLRP3-dependent pyroptosis was induced through SNHG7/miR-34a/SIRT1 signaling pathway during liver cancer." (PMID 34381023, 2021). "In liver cancer, SIRT1-mediated RANBP2 activation promotes progression of liver cancer." (PMID 33816306, 2021). "Given that HULC increases the expression of Sirt1 which is associated with deacetylation of LC3, we consider whether HULC influences on the autophagy through Sirt1 in liver cancer stem cells." (PMID 31900225, 2020). "SIRT1 also maintains the tumorigenic and self-renewal proprieties of liver cancer stem cells." (PMID 31608282, 2019). "In the present study, we found that hepatic neoplasm was an age-related disease, and resveratrol inhibited age-dependent spontaneous tumorigenesis by SIRT1-mediated post-translational modulations of K-Ras, FoxOs and DLC1 to proliferation and apoptosis in the annual fish." (PMID 28903430, 2017). "Moreover, SIRT1 induces expression of the transcription factor SOX2 to stimulate the self-renewal of liver cancer stem cells." (PMID 28881735, 2017). "Indeed, a number of studies have shown that SIRT1 is a putative oncogene and targeting SIRT1 is effective in inhibiting tumor growth and progression of liver cancer and chronic myeloid leukemia among others." (PMID 27708228, 2016). "Moreover, functional inhibition of SIRT1 with nicotinamide decreased tumorigenesis in c-Myc driving liver cancer animal models." (PMID 24019980, 2013). "In summation, our results suggest that SIRT1 cooperates with c-Myc in liver tumorigenesis and may be an important molecular target for modulating liver cancer." (PMID 23024800, 2012). "Therefore, to investigate the role of SIRT1 in liver cancer and its relationship to c-Myc, we utilized a mouse model of liver tumorigenesis under the genetic control of conditional oncogenic c-MYC." (PMID 23024800, 2012). "In the present study the role of SIRT1 in liver cancer was investigated." (PMID 23024800, 2012). "Therefore, patient cohort studies across different etiologies and disease stages are required to determine whether SIRT1 inhibition can be safely and effectively integrated into liver cancer therapy." (PMID 41008982, 2025).